CDC7 (cell division cycle 7)
Diseases named in the same sentence as CDC7 in open-access papers (continued):
Sharing a sentence is not in itself a finding about the gene and the disease.
adenocarcinoma (3 papers, 2024 to 2025). A common cancer characterized by the presence of malignant glandular cells. "Consistent with what we observed in adenocarcinoma cell lines, genetic (KO) or pharmacological inhibition of CDC7 again induced the activation of the proteasome." (PMID 39054323, 2024). "CDC7 inhibition with simurosertib suppresses targeted therapy-induced NE transformation in vivo and prolongs adenocarcinoma response to therapy." (PMID 39054323, 2024). "In the present work, we identify CDC7 inhibition as a potential therapeutic approach in two different settings: inhibition of NE transformation from adenocarcinomas on targeted therapy, and treatment of NE carcinomas, either de novo or following histological transformation." (PMID 39054323, 2024). "Both TD-NEPC and DU145, which express high levels of CDC7, were more sensitive to TAK-931 treatment compared to the adenocarcinoma cell lines including PC3, LNCaP-RFP, and RPWE-1, which express lower CDC7 levels." (PMID 41413594, 2025).
infection (2 papers, 2023 to 2024). The state of being infected such as from the introduction of a foreign agent such as serum, vaccine, antigenic substance or organism. "Taken together, these findings suggested that MVM infection at late stages of infection induces replication stress through the dysregulation of the replication kinase CDC7." (PMID 37253065, 2023). "Therefore, we hypothesized that ATR/CHK1 inactivation at late stages of infection dysregulates CDC7 and its ability to regulate new origin firing." (PMID 37253065, 2023). "MVM-induced replication stress and origin misfiring can be rescued by inhibiting CDC7 activity, as well as by overexpressing exogenous RPA during infection." (PMID 37253065, 2023). "Taken together, these results suggest that origin firing during a BKPyV infection uses the canonical kinases Cdc7 and Cdk2, and DDR activation does not prevent these kinases from firing origins as the newly licensed origins are fired prior to DDR activation." (PMID 39636788, 2024).
neurodegenerative disease (2 papers, 2021 to 2024). A disorder of the central nervous system characterized by gradual and progressive loss of neural tissue and neurologic function. "Biodegradable polymeric nanoparticles based on PLGA were obtained by the nanoprecipitation method and were loaded with PHA, a potent CDC7 inhibitor with great potential for some neurodegenerative diseases but with low brain permeability." (PMID 33525757, 2021).
benign tumors (1 paper, 2022). "Several studies have evaluated the expression of CDC7 in benign tumors." (PMID 36483932, 2022).
CDC7 also shares sentences with these, for which no sentence is quoted: amyotrophic lateral sclerosis (2 papers); Ewing sarcoma (2); leukemia (2); multiple myeloma (2); Primary Open Angle Glaucoma (2); prostate tumor (2); proteinopathies (2); Alzheimer disease (1); ampullary cancers (1); benign pancreatic tumors (1); central nervous system cancer (1); Cirrhosis (1); dysplastic nevi (1); Dystonia (1); kidney cancer (1); nodular melanomas (1); Obesity (1); oral cancer (1); prion disease (1); prostate (1); salivary gland malignant tumor (1); superficial spreading melanoma (1).